CHAC1 (ChaC glutathione specific gamma-glutamylcyclotransferase 1)
Diseases named in the same sentence as CHAC1 in open-access papers (continued):
Sharing a sentence is not in itself a finding about the gene and the disease.
tumor (continued). "Mice inoculated with HNSCC cells exhibiting stable CHAC1 suppression and treated with nisin exhibited statistically significant increased tumor volumes compared with controls, indicating that nisin effects are mediated via CHAC1 in vivo." (PMID 23342279, 2012). "Recent advances in research on ER stress, ferroptosis, and glutathione metabolism have progressively highlighted the critical contributions of the CHAC family, particularly CHAC1, to tumor progression, metastasis, and prognosis, establishing it as a focal point in oncology research." (PMID 40860820, 2025). "CHAC1 exhibits significant influence in the context of tumor development and progression." (PMID 39534397, 2024). "Additionally, overexpression of CHAC1 can enhance the sensitivity of tumor cells to chemotherapy by reducing intracellular GSH levels, thereby increasing oxidative stress and promoting cell death." (PMID 39534397, 2024). "The function of CHAC1 in tumorigenesis is tumor-type-specific." (PMID 39368995, 2024). "Additionally, CHAC1 expression was suppressed in tumor tissues compared to adjacent normal tissues in our clinical samples." (PMID 38007439, 2023). "Owing to the low basal level of CHAC1 in tumor cells, we speculated that tumoral CHAC1 expression might be elevated by CTL and then conferred to CTL-regulated ferroptosis." (PMID 37553341, 2023). "Considering that constitutively CHAC1 over-expression might directly affect tumor ferroptosis, we constructed the doxycycline (Doxy)-inducible CHAC1-Flag expressing B16F10 cells." (PMID 37553341, 2023). "Additionally, substantial inhibition of tumor growth was observed with CHAC1 overexpression, accompanied by a significant decrease in Ki67 expression within the tumor." (PMID 38007439, 2023). "We observed that Doxy-induced CHAC1 expression could enhance cystine deprivation-induced ferroptosis, and increase lipid peroxidation and tumor cell death in response to OT-I cells." (PMID 37553341, 2023). "Indeed, we found that CHAC1 mRNA expression in tumor cells was increased along the time after incubation with the supernatant from OT-I cells." (PMID 37553341, 2023). "Given that short-term methionine starvation promotes tumor cell ferroptosis by induction of CHAC1, we hypothesized that tumor cells undergoing short-term methionine starvation would become more sensitive to CTL-mediated killing." (PMID 37553341, 2023). "Important findings of our work described here are that NCX4040 induces a significant amount of ROS/RNS generation by inducing NOX4 enzymes which are responsible for the generation of O2•− in tumor cells, and induction of CHAC1 which leads to depletion of cellular GSH and oxidative stress." (PMID 36612280, 2022). "In the oral cancer mouse model, groups receiving nisin showed reduced tumour volumes through activation of CHAC1 expression when compared with controls, while pre-treating with nisin prior to and three weeks after tumour cell inoculation led to the same effect." (PMID 27853525, 2016). "Furthermore, nisin similarly prevents and inhibits the growth of HNSCC tumors in vivo via induction of CHAC1 expression, as its suppression significantly increases tumor volume." (PMID 23342279, 2012). "Importantly, in vitro experiments demonstrated that CHAC1 overexpression robustly induces cell death in ccRCC cell lines, suggesting it may exert a potential tumor-suppressive effect by promoting mechanisms like ferroptosis or apoptosis." (PMID 40860820, 2025). "We further analyzed whether CHAC1/PKM2 axis in vivo affected orthotopic xenograft tumor growth." (PMID 39368995, 2024).
tumor (continued). "CHAC1 is a downstream effector of several key signaling pathways, including the RhoA-ROCK1 and p38 MAPK pathways, which are modulated by tumor suppressors like ARHGAP6." (PMID 39534397, 2024). "Intermittent methionine deprivation also sensitizes tumor cells against CD8+ T cell-mediated cytotoxicity and synergize checkpoint blockade therapy by CHAC1 upregulation." (PMID 37553341, 2023). "Erastin treatment led to increased ChaC glutathione specific gamma-glutamylcyclotransferase 1 (CHAC1) staining and decreased recombinant solute carrier family 7, member 11 (SLC7A11) staining in sham tumor tissue that were well responsive to erastin." (PMID 36967385, 2023). "In summary, we have shown that CHAC1 induced by amino acid deprivation promotes GSH degradation, facilitates ferroptosis, and sensitizes tumor against T cell-mediated cytotoxicity." (PMID 37553341, 2023). "Accordingly, CHAC1 and PTGS2 mRNA expressions and lipid peroxidation marker 4HNE in tumor tissues were all elevated by the combination therapy compared with PD-1 blockade alone, and these inductions were also reversed by liproxstatin-1 co-treatment." (PMID 37553341, 2023). "As the results indicated, the expressions of CDCA3, MYCN and TFAP2A in ccRCC tumor tissue were significantly upregulated compared with those in adjacent normal kidney tissue, while the expressions of ACADSB and CHAC1 were significantly downregulated." (PMID 37064095, 2023). "Immunostaining of Rd76-9 cells for CHAC1, Ki-67, PH3 and Cleaved-Caspase 3 protein demonstrated that the depletion of CHAC1 decreased the numbers of Ki-67+ and PH3+ proliferating tumor cells as well as increased the number of tumor cells undergoing apoptosis." (PMID 36816948, 2023). "Recently, CHAC1 and NOX4, along with GPX4, have been suggested to be hallmarks of ferroptosis in tumor cells." (PMID 37371096, 2023). "In summary, five of the genes (CARS1, CHAC1, FANCD2, G6PD, and HMOX1) in the prognostic model have been reported to contribute to ferroptosis and to be upregulated in BC tumor tissue, in contrast to AIFM2." (PMID 36313179, 2022). "A mechanism of tumor cell death is proposed based on our findings where oxidative stress is induced by NCX4040 from simultaneous induction of NOX4, TNF-α and CHAC1 in tumor cell death." (PMID 36612280, 2022). "We further compared the expression of CHAC1 in KIRC samples with their paired normal samples, and found CHAC1 is significantly down‐regulated in tumour tissues with the P value of 3.438e‐16." (PMID 33728749, 2021). "The results demonstrated that the protein and mRNA levels of NFE2L1 and GPX4 were significantly increased in tumor tissues, whereas the ferroptosis marker proteins PTGS2, and CHAC1 were expressed at low levels in tumor tissues, however, SLC7A11 exhibited significant overexpression in tumor tissues." (PMID 41189569, 2025). "CHAC1, positioned within the eIF2α/ATF4 pathway activated during amino acid deprivation or ER stress, acts as a key executor by degrading GSH, exacerbating cysteine consumption, and thereby inducing ferroptosis in tumor cells." (PMID 40860820, 2025). "CHAC1 degrades intracellular glutathione (GSH) and promotes the ferroptosis of tumor cells." (PMID 39335604, 2024). "Furthermore, SUMO-modified PKM2 nuclear translocation activates the transcription of proliferation- and glycolysis-related genes, and CHAC1 promotes LUAD glycolysis and tumor progression." (PMID 39368995, 2024). "Conversely, the depletion of CHAC1 in PC9 cells reduced the size and number of tumor spheres." (PMID 39368995, 2024). "Tumor growth curve and terminal tumor weight were similar between the WT and KI groups, indicating CHAC1 inactivation in the host does not impact tumor growth." (PMID 37014882, 2023). "The observation that glutathione in Pan02 tumor-bearing Chac1 KI mice was not rescued to the same level as in NTB KI mice suggests additional mechanisms contributed to glutathione depletion in this model." (PMID 37014882, 2023).
tumor (continued). "CHAC1 protein levels in shChac1 RMS tumor cells were decreased compared to non-targeting control, confirming efficient Chac1 depletion." (PMID 36816948, 2023). "Moreover, ChaC Glutathione Specific Gamma-Glutamylcyclotransferase 1 (CHaC1) also regulates GSH degradation and has been detected to be downregulated in some tumor cells." (PMID 36105219, 2022). "Furthermore, it is very interesting to note that induction of CHAC1 and NOX4, two genes significantly induced by NCX4040, have been suggested to be biomarkers for ferroptosis-related cell death in tumor cells." (PMID 36612280, 2022). "Additionally, CHAC1 has been discovered to decease intracellular GSH levels, enhancing tumor cell ferroptosis." (PMID 34900981, 2021). "Notably, inhibiting the ferroptosis regulators CHAC1 and ACSL4 in A375 cells reversed these effects, highlighting ferroptosis as a critical mediator of T-cell activation, potentially through the release of immunogenic signals from dying tumor cells." (PMID 40860143, 2025). "Similarly, in various other tumor cell lines including OS-RC-2, 786-O and SNU387 cells, forced CHAC1 expression was able to enhance ferroptosis induced by cystine deprivation or erastin treatment and recover ferroptosis inhibited by simultaneous methionine deprivation." (PMID 37553341, 2023). "However, among these tumour samples with different T stages and total stages, we found KIRC samples extracted from higher T stage or higher total stage usually exhibit relatively higher CHAC1 mRNA or protein expression." (PMID 33728749, 2021). "Increased CHAC1 mRNA expression was found in tumours lacking ER (P<0.001) and PR (P<0.001)." (PMID 22108517, 2012). "Although future in-depth studies may be worth to fully understand the role of methionine intermittent deprivation on tumor metabolism and antitumor immunity, we find here that short-term methionine starvation can cooperate with CD8+ T cells to induce tumoral ferroptosis by converging on CHAC1." (PMID 37553341, 2023). "Although CHAC1 is known to hydrolyze glutathione, leading to the depletion of GSH in tumor cells, our study does not show the depletion of GSH in either cell line." (PMID 37371096, 2023).
infection (13 papers, 2016 to 2025). The state of being infected such as from the introduction of a foreign agent such as serum, vaccine, antigenic substance or organism. "The increase in Chac1, which encodes glutathione-specific gamma-glutamylcyclotransferase 1, an enzyme that degrades glutathione, would further support a reduction in antioxidant capacity in mice following infection." (PMID 40618034, 2025). "To systematically identify GSH-sensitive chemotherapeutics, we constructed GSH-depleted HCC cells through infection of ChaC1-expressing adenovirus (Ad-ChaC1)." (PMID 41249117, 2025). "On the other hand, certain genes involved in glutathione biosynthesis and recycling (Chac1, Oplah, and Ggt5) were upregulated, highlighting the complex impact of the infection on liver metabolic functions." (PMID 40618034, 2025). "The PERK branch of UPR-associated genes, including ATF4, ATF5 CHAC1, PDI, and DDIT3, were upregulated upon infection." (PMID 35368019, 2022). "Using cellular infection models, other transcriptomic studies have consistently shown CHAC1 upregulation with microorganisms, including human coronavirus, human cytomegalovirus, tick-borne flaviviruses, Zika virus, and the bacterium Mycoplasma hominis." (PMID 30555487, 2018). "A similar trend of gene expression was observed in murine macrophages at 24 h post-infection (infection index 83 ± 33) with few differences regarding the expression of Chac1 and Cebpb." (PMID 27978534, 2016). "In Helicobacter pylori-driven gastric carcinogenesis, infection sharply upregulates CHAC1." (PMID 41488051, 2025). "However, there have been conflicting reports regarding the transcriptional regulation of CHAC1 during infection, and our data suggest that hydrolysis of host GSH to Cys-Gly in H. pylori-infected cells is gGT-dependent." (PMID 37494402, 2023). "The knockdown of HSP90 significantly increased the GPX4 expression levels, decreased CHAC1 mRNA levels, and reduced intracellular iron content post-ETEC infection, suggesting that the reduction in HSP90 blocked the occurrence of ferroptosis." (PMID 40867813, 2025). "Our results found that the expression of ER stress marker genes ATF4, CHOP, and CHAC1 were up-regulated in Ms_Rv0580c infected THP-1 macrophages as compared to Ms_pNIT infected THP-1 macrophages, at 24 h post-infection." (PMID 33535567, 2021). "In tests of infection with other paramyxoviruses, Nipah virus (NiV) and Hendra virus (HeV), CHAC1 expression was not upregulated." (PMID 38635661, 2024). "We found that DDIT4, CTH, RELB, and SLC7A11, but not NDRG1 and CHAC1, increased in gastric tissues at 4 months post-infection (MPI)." (PMID 32457731, 2020). "In a previous transcriptomic analysis, we identified CHAC1 as one of the differentially expressed mRNAs between human airway epithelial cells from bronchi (hAECBs) of patients with and without CF during Pa infection." (PMID 30555487, 2018). "First, we confirmed by reverse transcription quantitative polymerase chain reaction that CHAC1 mRNA was overexpressed in hAECBs from patients without CF compared with the expression in hAECBs from patients with CF upon Pa (PAK strain) infection." (PMID 30555487, 2018). "Among these dysregulated mRNAs, ChaC glutathione-specific γ-glutamylcyclotransferase 1 (CHAC1) showed dramatically differential expression between non-CF and CF cells both at baseline and after Pa infection." (PMID 30555487, 2018). "We confirmed our previous transcriptomic data showing that CHAC1 mRNA was overexpressed in primary non-CF epithelial cells compared with its expression in CF cells at baseline and upon Pa infection." (PMID 30555487, 2018). "As expected from the transcriptomic data, we observed upregulation of CHAC1 mRNA expression after 6 h of Pa infection only in non-CF cells." (PMID 30555487, 2018).
infection (continued). "Consistent with previous reports indicating that CHAC1 protein is very unstable due to its rapid degradation by the proteasome in Neuro2a cells, we were unable to detect endogenous CHAC1 protein in NCI-H292 at baseline or after Pa infection (data not shown)." (PMID 30555487, 2018).
cardiovascular diseases (2 papers, 2019 to 2024). "Additionally, CHAC1 influences non-cancerous diseases such as neurodegenerative and cardiovascular disorders." (PMID 39534397, 2024).
neurodegenerative disease (2 papers, 2024 to 2025). A disorder of the central nervous system characterized by gradual and progressive loss of neural tissue and neurologic function. "As an inducer of ferroptosis, inhibiting CHAC1-induced cell death may also hold therapeutic relevance for conditions like neurodegenerative diseases." (PMID 41488051, 2025).
bacterial infection (1 paper, 2019). "Additionally, CHAC1 expression leads to increased inflammation during bacterial infection." (PMID 31781116, 2019).
kidney disease (1 paper, 2025). "In kidney disease, CHAC1 upregulation was induced by cysteine and methionine deprivation, treatment with erastin and exposure to tunicamycin." (PMID 41488051, 2025). "Similarly, CHAC1 is upregulated in various kidney disease models." (PMID 41488051, 2025).
metabolic disorders (1 paper, 2024). "In summary, CHAC1 is a crucial mediator of oxidative stress, inflammation, and cell death across various diseases, from neurological and metabolic disorders to infectious, respiratory, and chronic inflammatory conditions." (PMID 39534397, 2024).
myopathy (1 paper, 2024). A disease of the muscle in which the muscle fibers do not function properly. "Brothers and colleagues identified upregulated CHAC1 in the WB of 3-week-old male broilers and suggested that CHAC1 may degrade glutathione in the P. major, making the tissue more susceptible to oxidative stress, ultimately contributing to the development of myopathies." (PMID 38254345, 2024). "The reasons for CHAC1 downregulation in both SM and WB in our cohort are uncertain; however, differences with previous studies may reflect different stages of myopathy progression." (PMID 38254345, 2024).
respiratory diseases (1 paper, 2024). "In respiratory diseases, such as bleomycin-induced lung injury and bronchopulmonary dysplasia, CHAC1 contributes to the resolution of inflammation by promoting the apoptosis of immune cells, but its role in oxidative stress also highlights its damaging potential." (PMID 39534397, 2024).
CHAC1 also shares sentences with these, for which no sentence is quoted: endometrial cancer (2 papers); inflammation (2); lung squamous cell carcinoma (2); renal cell carcinoma (2); stomach adenocarcinoma (2); asthma (1); atopic dermatitis (1); Autoimmunity (1); bladder urothelial carcinoma (1); brain tumour (1); cervical cancer (1); cervical squamous cell carcinoma (1); cholangiocarcinoma (1); chronic kidney disease (1); colon adenocarcinoma (1); COVID-19 (1); endocervical adenocarcinoma (1); fibrosarcoma (1); ischemic heart disease (1); myocardial ischemia (1); nasopharyngeal carcinoma (1); neurological disorders (1); Obesity (1); oral cancer (1); oral squamous cell carcinoma (1); pancreatic adenocarcinoma (1); rectum adenocarcinoma (1); subarachnoid hemorrhage (1); thyroid carcinoma (1); uterine carcinosarcoma (1).
A further 2 diseases each share a sentence with CHAC1 in 1 paper.